CXCL1 (C-X-C motif chemokine ligand 1)
Diseases named in the same sentence as CXCL1 in open-access papers (continued):
Sharing a sentence is not in itself a finding about the gene and the disease.
pancreatic cancer (continued). "Mechanistically, Regnase-1 directly negatively regulated a variety of chemokines/cytokines important for MDSC recruitment and activation, including CXCL1, CXCL2, CSF2, and TGFβ, in pancreatic cancer cells." (PMID 37814340, 2023). "In pancreatic cancer, APOE involved the expression of Cxcl1 and Cxcl5, known immunosuppressive factors, leading to immunosuppression." (PMID 35216190, 2022). "ONCOMINE data showed that in addition to CXCL1, CXCL4, CXCL11 and CXCL12, the mRNA levels of the other 12 CXC chemokines were significantly increased in pancreatic cancer." (PMID 35468838, 2022). "Treatment with KC-conditioned media on CAFs induces secretion of CXCL1, CXCL5, and CXCL7 greater than treatment with conditioned media from KRAS wild-type pancreatic cancer cells." (PMID 35159011, 2022). "Primary pancreatic cancer cells from Ptf1a-Cre; lox-stop-lox-KrasG12D/+; Tgfbr2lox/lox mice secrete CXCR2 ligands including CXCL1, CXCL2, and CXCL5." (PMID 35159011, 2022). "CXCL1, CXCL5, CCL2, and IL-8 were significantly induced by TRAIL in lung, colorectal and pancreatic cancer cell lines." (PMID 31010082, 2019). "Serum levels of GM-CSF in pancreatic cancer patients are also significantly higher than in healthy individuals, and increased expression of the inflammatory cytokines IFN-γ, CXCL1 and CXCL2 were observed in a mouse model of spontaneous pancreatic cancer." (PMID 29245934, 2017). "For example, CXCL1 and CXCL5, secreted by pancreas cancer cells, can activate CXCR2 in fibroblasts to stimulate the production of connective tissue growth factor that, in turn, fuels tumor progression." (PMID 26327350, 2015). "ENA-78/CXCL5 and GRO-α/CXCL1 have been shown to have increased expression in tumors of patients with malignant versus non-malignant pancreas tumors, suggesting a role for these genes in pancreatic carcinogenesis." (PMID 39989973, 2025). "Furthermore, senescence-induced pancreatic stellate cells secrete CXCL1, CXCL2, and CXCL3, and blockade of the CXCR2 axis suppresses pancreatic cancer cell proliferation." (PMID 41155662, 2025). "Instead, CXCL1 played a role in promoting angiogenesis in a paracrine manner in human vascular endothelial cells (HUVECs), and blocking CXCR2 in an orthotopic murine pancreatic cancer model reduced the tumor volume and inhibited the microvessel density." (PMID 38339310, 2024). "Additionally, the higher expression of the human homolog of mouse Cxcl5, CXCL6, and other ligands of CXCR2 (CXCL1 and CXCL2) was also identified in human pancreatic cancer cells after adding AMP." (PMID 37867243, 2023). "Furthermore, numerous pro-inflammatory cytokines, including IL-6, TNF-α, chemokine (C-X-C motif) ligand 1 (CXCL-1), and CXCL-6 are found in the TME of pancreatic cancer cells." (PMID 37629174, 2023). "Expression of CXCL1 is dependent on receptor-interacting protein 1 (RIP1) and RIP3, key regulators for necroptosis (programmed necrosis), which are also highly expressed in human pancreatic cancer." (PMID 35159011, 2022). "Unfortunately, none of the data assessed the protein expression of CXCL1/2/3/6/9/10/17 in pancreatic cancer and normal tissues." (PMID 34497764, 2021). "Of note, analysis of pancreatic cancer and normal tissue datasets from TCGA and GTEx databases revealed a positive correlation between SQLE and CXCL1 expression in clinical samples, indicating that the regulation of CXCL1 by SQLE/Squalene likely occurred in vivo." (PMID 39763673, 2024). "Furthermore, we identified CXCL1, CXCL2, and CXCL3 as SASP factors secreted by senescence-induced hPSCs, and the inhibition of the CXCLs/CXCR2 axis attenuated their stimulating effects on the proliferation and migration of pancreatic cancer cells." (PMID 36012531, 2022). "ENA-78/CXCL5 and GRO-α/CXCL1 are of particular interest, as they are upregulated in NHB patients independent of CCa status and pancreas tumor type." (PMID 39989973, 2025).
atherosclerosis (52 papers, 2007 to 2025). A disease characterized by the build-up of fatty material and calcium deposition in the arterial wall resulting in partial or complete occlusion of the arterial lumen. "Polymorphisms in the Cx3cl1 receptor, Cx3CR1, have been identified as genetic risk factors for atherosclerosis, and the deletion of Cx3cl1, Cx3CR1 and Cxcl1 suppresses atherogenesis." (PMID 38473793, 2024). "Accordingly, we found that endothelial Dicer deficiency downregulates CXCL1 in murine arteries and reduces the adhesion of monocytes to the endothelium during the early stage of atherosclerosis." (PMID 26837267, 2016). "Disruption of miRNA biogenesis in ECs by endothelial Dicer deletion reduced the expression of CXCL1 in the arteries of apolipoprotein E-deficient mice, thereby attenuating monocyte adhesion to early atherosclerosis-prone endothelium." (PMID 26001902, 2015). "Cxcl1 and Cxcr2 are also implicated in mobilization of monocytes, in models of atherosclerosis and is Cxcr2 expressed by CNS- and retinal-derived monocytes." (PMID 25595590, 2015). "Inhibition of the LPA-mediated CXCL1 release impairs monocyte adhesion and atherosclerosis in apolipoprotein E-deficient mice." (PMID 26001902, 2015). "CXCL1 has been mechanistically linked to the pathogenesis of cardiovascular disorders, particularly atherosclerosis and coronary artery disease, through its ability to exacerbate vascular inflammation by promoting pro-inflammatory responses within the vascular endothelium." (PMID 40176796, 2025). "MiR-103 increased CXCL1-dependent monocyte adhesion and rescued the decreased chemokine expression caused by knockdown of Dicer in ECs, indicating that reduced endothelial miR-103 levels limit monocyte adhesion and atherosclerosis in EC-Dicerflox mice by downregulating CXCL1." (PMID 26837267, 2016). "Oxidation-modified low-density lipoprotein (ox-LDL) promotes atherosclerosis through the release of CXCL1, a chemokine that is anchored to the surface of endothelial cells, facilitating monocyte adhesion and the progression of atherosclerosis." (PMID 40299531, 2025). "Endothelial HIF-1α promotes atherosclerosis by triggering miR-19a mediated CXCL1 expression and monocyte adhesion." (PMID 40478326, 2025). "Intersection of three datasets: our Ninj1-associated DEGs, atherosclerosis-related genes from GSE57691, and inflammation-associated genes from DisGeNET C0021368, yielded 11 overlapping genes including CXCL-8, TNFAIP3, and CXCL-1." (PMID 41280941, 2025). "Blocking the LPA receptors 1 and 3 reduced hyperlipidemia-induced arterial leukocyte arrest and atherosclerosis in the presence of functional CXCL1, indicating that hyperlipidemia-induced monocyte recruitment depends on LPA." (PMID 37059333, 2023). "LPA accelerates the progress of atherosclerosis and recruits leukocytes to the vessel wall via the release of CXCL1 mediated by LPA1 and LPA3." (PMID 37569902, 2023). "Activation of LPAR1 and LPAR3 can promote the expression of hypoxia-inducible factor 1 subunit alpha (HIF-1α), then upregulate C-X-C motif chemokine ligand 1 (CXCL1) in cells, thereby accelerating atherosclerosis." (PMID 37342437, 2023). "During the early phase of atherosclerosis, CXCL1 promotes the accumulation of macrophages and induces monocyte arrest in the vessel wall." (PMID 37569902, 2023). "CXCL1 promotes the development of atherosclerosis by regulating the migration, diffusion, and differentiation of macrophages." (PMID 35668739, 2021). "Chemokines are essential in orchestrating the development of atherosclerosis, from the initial stage of endothelial dysfunction, chemokines like CXCL1 act as a chemoattractant for several immune cells." (PMID 33503867, 2021).
atherosclerosis (continued). "Inhibiting the interaction between miR-103 and KLF4 reduces atherosclerosis, lesional macrophage accumulation and endothelial CXCL1 expression." (PMID 26837267, 2016). "Blocking the interaction between miR-103 and KLF4 in arteries reduced atherosclerosis, lesional macrophage accumulation and CXCL1 expression, similar as the deletion of Dicer in ECs." (PMID 26837267, 2016). "Inhibition of the miR-103-KLF4 interaction reduced atherosclerosis, lesional macrophage accumulation and endothelial CXCL1 expression in the arteries of Apoe−/− mice, indicating a proinflammatory and proatherogenic role of miR-103 by targeting KLF4." (PMID 26837267, 2016). "CXCL1 is also involved in atherosclerosis, and LPAR3 is required for monocyte recruitment to atherosclerotic lesions by oxidized LDL." (PMID 25965835, 2015). "We have previously shown that sympathetic activation by social disruption stress in ApoE−/− mice not only accelerates atherosclerosis but also increases plasma levels of CXCL1." (PMID 25105129, 2014). "Under some pathologic conditions, such as Atherosclerosis, CXCL1 trigger monocytes adhesion and recruitment to endothelium lesion." (PMID 23967336, 2013). "During early atherosclerosis, CXCL1/GRO-α immobilized on the surface of endothelial cells via heparin proteoglycans induces the firm adhesion of rolling monocytes expressing CXCR2." (PMID 22807925, 2012). "Endothelial cells release CXCL1 when induced by oxLDL, and high levels of CXCL1 can lead to leukocyte recruitment and migration to the carotid bifurcation, accelerating the progression of atherosclerosis." (PMID 40535169, 2025). "In contrast, Cxcl1 and Cx3cl1 have been reported to promote atherosclerosis." (PMID 38473793, 2024). "CXCL1 not only plays a significant role in inflammatory response but also participates in a variety of biological processes, such as angiogenesis tumor genesis, atherosclerosis, wound healing, and so on." (PMID 35401213, 2022). "CXCL1 is another element in the pathophysiology of atherosclerosis." (PMID 36613652, 2022). "Hematopoietic deficiency of CXCL1 did not alter atherosclerosis, suggesting that the atherosclerotic effects of CXCL1 were attributable to non-hematopoietic cells." (PMID 33503867, 2021). "Adhesion molecules such as VCAM-1 and ICAM-1 and chemokines such as MCP-1/JE and CXCL1/KC are important modulators in monocyte recruitment, rolling, and adhesion to the vascular endothelium and play a fundamental role in the pathogenesis of atherosclerosis." (PMID 34830366, 2021). "Both CXCL1 and E-selectin mediate leukocyte recruitment from blood to plaques and hence play a crucial role in the early stages of atherosclerosis when dysfunctional EC secrete chemokines/upregulate adhesion molecules and thereby induce monocyte and neutrophil adhesion." (PMID 33185739, 2020). "In line with this, systemic absence of CXCL1 or hematopoietic CXCR2-deficiency has been shown to be protective against atherosclerosis in mice by reducing the intra-plaque macrophage accumulation." (PMID 31191301, 2019). "Moreover, a recent study has shown that in vivo, lysophosphatidic acid increased the progression of atherosclerosis and recruited leukocytes to the vessel wall during early atherogenesis via lysophosphatidic acid receptor-mediated release of endothelial CXCL1." (PMID 22807925, 2012). "Studies in knockout mice suggested that CXCL-1 and its receptor is important after early lesions have been established which implies a delayed expression relative to the onset of atherosclerosis whereas 18F-FDG uptake is increased from early in the atherogenesis." (PMID 23226424, 2012). "In rat atherosclerosis PCR array, Abca1, Bax, Bcl2, Bcl2a1, Cd44, Fabp3, Hbegf, Lypla1, Ptgs1, Selplg, Tgfb2, Tnc, and Vegfa had reverse trend between WT and MU groups, while the trends of Bcl2l1, Bid, Birc3, Cxcl1, Fas, Fn1, Itga2, Itga5, Lif, Nfkb1, Nr1h3, Ppard, and Sod1 were consistent." (PMID 34545275, 2021).
atherosclerosis (continued). "However, another study showed that CXCL1 stabilises plaques in the late stages of atherosclerosis." (PMID 35668739, 2021). "Also, the observed increased atherosclerotic plaque formation and more numerous neutrophils, Ly6Chigh monocytes, and macrophages inside plaques of ApoE−/−Svep1+/− compared to ApoE−/−Svep1+/+ mice accord with the downstream effects of CXCL1 and E-selectin in atherosclerosis." (PMID 33185739, 2020). "Therefore, elevated levels of CARD8 in atherosclerosis may therefore contribute to increased inflammation in the pathogenesis of atherosclerosis by upregulation of CXCL1, CXCL6, IL-6 and possibly also MCP-1, may aggravate atherosclerosis." (PMID 33154409, 2020). "A comparison of the extent of atherosclerotic lesion formation between Cxcr2-deficient and Cxcl1-deficient atheroprone mice, i.e., comparing receptor versus ligand knockouts, prompted studies into potential additional CXCR2 ligands with a role in atherosclerosis." (PMID 31195722, 2019). "Moreover, increased expression of miR-19a can induce the expression of chemokine C-X-C motif ligand 1 (CXCL1) in mildly oxidized low-density lipoprotein–stimulated endothelial cells, and CXCL1 is important in the recruitment of atherogenic monocyte in the initiation of atherosclerosis." (PMID 31703587, 2019). "For instance, current evidence suggests that the therapeutic application of miR-181b may limit the release of CXCL1 from the vascular endothelium and thereby reducing atherosclerosis, whereas the endothelial delivery of miR-126-3p boosts atheropotective CXCL12 expression." (PMID 26001902, 2015). "Indeed, the chemokines growth-related oncogene (GRO)-α/CXCL1 interleukin (IL)-8/CXCL8 and monocyte chemoattractant protein (MCP)-1/CCL2 have all been implicated in the pathogenesis of atherosclerosis, at least partly through their ability to attract and activate leukocytes into the vessel wall." (PMID 22815786, 2012). "Atherosclerosis-model mice treated with exendin-4, another GLP-1RA, also demonstrated reduced circulating levels of monocyte chemoattractant protein-1, C-X-C motif chemokine ligand-1 (CXCL-1), and ultimately neutrophil recruitment." (PMID 40777992, 2025). "Treatment with DNase I decreased NET formation and ameliorated atherosclerosis in ApoE−/−PAD4 KO mice, reducing levels of IL-1β, TNFα, CCL2, CXCL1, and CXCL2 under both in vitro and in vivo conditions." (PMID 40786884, 2025). "CXCL1/CXCR2 signaling are widely studied in cardiovascular diseases, including cardiac hypertrophy, hypertension, aneurysm, and atherosclerosis." (PMID 38601164, 2024). "These mice exhibited increased expression of several genes of the CXC chemokine gene cluster, including CXCL1, CXCL2, CXCL3, and Pf4, and classic proinflammatory cytokine genes such as IL-1ß and IL-6, which contribute to atherosclerosis." (PMID 38162500, 2023). "This was evidenced by a consistent macrophage phenotype characterized by significant upregulation of CXCL1, CXCL2, CXCL3, and IL-6, ultimately contributing to the promotion of accelerated atherosclerosis." (PMID 38162500, 2023). "Finally, CXCL1 may also participate in atherosclerosis regression." (PMID 36613652, 2022). "Numerous studies have demonstrated the importance of the CCR2/CCL2 (MCP-1), CX3CR1/CX3CL1 (fractalkine), CXCR2/CXCL1, and CCR5/CCL2/CCL5 interactions in the progression of experimental atherosclerosis." (PMID 31195722, 2019). "OxLDL has been shown to induce Cxcl1 expression in macrophages via a co-operation of CD36/TLR4/TLR6, and CXCL1 represents a key mediator of leukocyte recruitment in atherosclerosis." (PMID 26947073, 2016). "The receptor for CXCL1 CXCR2 is present on myeloid cells like neutrophils and monocyte/macrophages, which are directly involved in all aspects of atherosclerosis." (PMID 24879339, 2014).
atherosclerosis (continued). "Several chemokines including CXCL1/growth-related oncogene (GRO)-α, CXCL8/interleukin (IL)-8 and CCL2/monocyte chemoattractant protein (MCP)-1 are important in the pathogenesis of atherosclerosis and can be influenced by statin-treatment." (PMID 22815786, 2012). "Additionally, PAD4’s interactions with CXCL1, PDIA1, and miR-155, as well as its involvement in NLRP3 inflammasome activation, underscore its multifaceted impact on inflammation and atherosclerosis." (PMID 40786884, 2025). "In our study, p.L245P-macrophages expressed higher levels of CXCL1 and CXCL8 than WT-macrophages and thus may exert a pro-inflammatory effect in the pathogenesis of atherosclerosis." (PMID 38806571, 2024). "Thus, we proposed that CXCL1 and CXCL8 might be two effectors of the protective role of PCB2 in atherosclerosis progression." (PMID 38679696, 2024). "Unsaturated LPA was found to release C-X-C motif chemokine ligand 1 (CXCL1) from endothelial cells, which was subsequently, immobilized on the cell surface to mediate LPA-induced monocyte adhesion, and systemic LPA accelerated the progression of atherosclerosis in mice." (PMID 37059333, 2023). "Compared with mice treated with control LNAs, treatment with lncWDR59-TSBs reduced atherosclerosis, the necrotic core area, and endothelial DNA damage, and increased EC proliferation, whereas the fibrous cap thickness and the Cxcl1-expressing ECs were not affected." (PMID 29980665, 2018). "Concomitantly in mice lacking Cxcl1, atherosclerosis is significantly reduced." (PMID 24879339, 2014).